SMIM30 (small integral membrane protein 30)
Description:
Negatively regulates antiviral innate immune responses. Disrupts the interaction of antiviral protein MAVS with innate immune receptor RIGI and inhibits MAVS aggregation, resulting in the repression of type I interferon signaling and innate immune responses.
Synonyms: MAVI1; LINC00998
Tractability: Antibody: UniProt predicts a signal peptide or a membrane-spanning region.
Gene: Protein-coding gene on chromosome 7 (113,116,718 to 113,118,582, reverse strand). Ensembl gene ENSG00000214194.
Subcellular location: Endoplasmic reticulum membrane; Mitochondrion membrane
Gene Ontology:
Molecular function: protein binding
Biological process: negative regulation of type I interferon-mediated signaling pathway
Cellular component: endoplasmic reticulum membrane; mitochondrial membrane
Homologues: Orthologues: chimpanzee SMIM30 (100% identical), guinea pig SMIM30 (97% identical), rabbit SMIM30 (97% identical), pig SMIM30 (93% identical), mouse Smim30 (92% identical).
Diseases named in the same sentence as SMIM30 in open-access papers:
SMIM30 is named in the same sentence as 14 diseases in open-access papers, as found by Europe PMC text mining. Sharing a sentence is not in itself a finding about the gene and the disease. The quoted sentences say what the papers report.
hepatocellular carcinoma (9 papers, 2021 to 2025). A malignant tumor that arises from hepatocytes. "Silencing SMIM30 inhibited the proliferation of hepatoma cells in vitro and suppressed the growth of tumor xenografts and N‐nitrosodiethylamine‐induced hepatoma." (PMID 36495128, 2023). "In addition, we evaluated the role of SMIM30 in the development of DEN‐induced hepatoma using a SMIM30 knockout mice." (PMID 36495128, 2023). "Another interesting example is SMIM30 that controls cell migration and proliferation in hepatocellular carcinoma (HCC) and can be targeted in HCC diagnosis, prognosis, and therapy." (PMID 40842332, 2025). "SMIM30 promotes hepatocellular carcinoma tumorigenesis by regulating cell proliferation and migration, and its level is related to the poor survival of HCC patients." (PMID 35127486, 2021). "Functional analysis showed that SMIM30, but not LINC00998, promoted the G1/S transition and proliferation of hepatoma cells by reducing the cytosolic calcium level." (PMID 36495128, 2023).
glioblastoma (3 papers, 2020 to 2023). The most malignant astrocytic tumor (WHO grade IV). "Further validation by RT-qPCR revealed SMIM30, SNORA53 and LINC01354 were significantly upregulated and EFEMP2 markedly downregulated in 15 glioblastoma samples compared to 6 controls samples." (PMID 32962742, 2020).
acute myeloid leukemia (2 papers, 2021 to 2022). Acute myeloid leukemia (AML) is a group of neoplasms arising from precursor cells committed to the myeloid cell-line differentiation. "In addition, tumor-associated micropeptides have also been found in liver cancer, rectal cancer, glioma, acute myeloid leukemia (AML) and other cancers, such as SMIM30, MPM (micropeptide in mitochondria), ASAP (ATP synthase-associated peptide), APPLE (a peptide located in ER)." (PMID 36117171, 2022).
allergic asthma (1 paper, 2023). A asthma with a basis in a pathological type I hypersensitivity reaction. "Similar to the microarray data results for PBMCs of patients with allergic asthma, the transcript-level expression of SMIM30 and MIR222HG was significantly decreased in PBMCs of AR patients when compared with those in the controls." (PMID 37205104, 2023).
liver cancer (1 paper, 2022). An epithelial or non-epithelial malignant neoplasm that arises from the liver. "SMIM30 promotes the proliferation and migration of liver cancer cells both inside and outside the body." (PMID 35962317, 2022).
tumor (4 papers, 2020 to 2025). "Overexpression of the 5′UTR‐sORF sequence of LINC00998, encoding wild‐type SMIM30, enhanced tumor cell growth, but this was abolished when a premature stop codon was introduced into the sORF via single‐base deletion." (PMID 36495128, 2023). "To explore the molecular underpinnings of SMIM30 in tumor growth, we performed GSEA to identify the SMIM30‐associated pathways by using the transcriptome data of human HCC tissues derived from TCGA." (PMID 36495128, 2023). "The findings from Yang’s report indicated that the micropeptide SMIM30, encoded by LINC00998, was upregulated in various malignancies and promoted tumor growth by reducing cytosolic calcium levels and promoting G1/S transition." (PMID 41291707, 2025). "Compared with control group, SMIM30‐silencing tumor cells displayed a significant reduction of cell growth and colony formation." (PMID 36495128, 2023). "SMIM30 was upregulated in various malignancies and it promoted the G1/S transition by reducing cytosolic calcium level, thereby enhancing cell proliferation and tumor growth." (PMID 36495128, 2023). "Moreover, SMIM30 was upregulated in multiple types of malignancies and silencing SMIM30 inhibited tumor growth in vivo." (PMID 36495128, 2023). "We further evaluated whether SMIM30 affected tumor growth in vivo." (PMID 36495128, 2023). "As shown, 66.7% (2/3) of SMIM30‐wildtype mice developed tumors in the liver, whereas none (0/5) of SMIM30‐KO mice developed tumor." (PMID 36495128, 2023).
cancer (2 papers, 2023 to 2024). A tumor composed of atypical neoplastic, often pleomorphic cells that invade other tissues. "We then explored whether SMIM30 plays a role in cancer development." (PMID 36495128, 2023).
SMIM30 also shares sentences with these, for which no sentence is quoted: glioma (2 papers); major depressive disorder (2); cervical cancer (1); gastric cancer (1); malignant glioma (1); non-small cell lung carcinoma (1); triple-negative breast carcinoma (1).